WT1 (WT1 transcription factor)
Diseases named in the same sentence as WT1 in open-access papers (continued):
Sharing a sentence is not in itself a finding about the gene and the disease.
Wilms tumor (continued). "Studying WT1 not only is promising in leading to deeper insights in Wilms Tumor, but it is also a marker of the MM during nephrogenesis and therefore helpful to determine its function in organ development better." (PMID 36120564, 2022). "Collectively, we report for the first time that a heterozygous c.1387C>T variant of WT1 was associated with non–syndromic POI and Wilms’ tumor in a Chinese family." (PMID 34845858, 2022). "Pathogenic variants in the WT1 gene were found to be associated with Denys-Drash syndrome, in which SRNS is accompanied by nephroblastoma, disorder of sex development and testicular/ovarian cancer." (PMID 35610319, 2022). "Mutations in WT1 were reported in the blastic phase CML32, Wilms tumor and desmoplastic small round cell tumor (COSM21401)." (PMID 35896598, 2022). "We were interested to study the effect of Canagliflozin on podocyte health by quantifying the exosome expression for Nephrin, Wilm’s Tumor (WT-1) and podocalaxyn like protein 1 (PODXL) in urine samples from placebo and Canagliflozin group." (PMID 33581737, 2021). "WT-1 is necessary for the development of critical organs, including the kidneys, and also plays a role as a tumor suppressor against the formation of Wilms’ tumor, a cancer of the kidneys." (PMID 34314463, 2021). "Wilms tumor can arise as a consequence of abnormal genetic changes in the 11p13 (WT1) and 11p15 (WT2) regions of the short arm of chromosome 11." (PMID 35187045, 2021). "All cases of Wilms’ tumor showed heterogeneous to diffuse cytoplasm/nuclear expression of WT1 in both the epithelial and blastemal component; a diffuse immunostaining for CD56 was also documented in the blastemal component." (PMID 34943491, 2021). "Genomic imprinting at the WT1 gene involves its alternative coding transcript (AWT1) that shows deregulation in Wilms’ tumors." (PMID 33572862, 2021). "N-myc, WT1, and RB1 genes are associated with NB, nephroblastoma, RB, and other tumors, respectively." (PMID 33259778, 2021). "In this study, we present a patient with Wilms tumor, a female appearance, and a 46, XY karyotype who had previously unreported mutations in exon 9 in the ZF3 region of WT1." (PMID 33942367, 2021). "In this regard we strongly suggest the use of antibodies directed aganist the C-terminus WT1 protein (clone WTC19) which are more specific to Wilms’ tumor (exclusive nuclear staining of the neoplastic blastemal cells)." (PMID 34943491, 2021). "Wilms tumor 1 (WT1) is a tumor-suppressor gene coding for a zinc finger transcription factor located on chromosome 11p13, and was originally identified in Wilms’ tumor." (PMID 34638574, 2021). "A study identified an antisense regulatory region in intron 1 of the WT1 gene, located on chromosome 11p13, in Wilms’ tumors as a primary site for epigenetic deregulation." (PMID 34777476, 2021). "In the adult CPDN cases, only one case was positive for WT1 protein, which is positive in most cases of Wilms tumor." (PMID 34755065, 2021). "Although WT1 is known to act as a tumor suppressor in Wilms tumor, it seems to be an oncogene in other neoplasms." (PMID 33593440, 2021). "Although Wilms’ tumor shows nuclear staining with WT1, its diagnosis is usually straightforward if we are dealing with a renal tumor mass with a mixed component (blastemal and epithelial components)." (PMID 34943491, 2021). "Its presence has been determined in cell lines and specimens of Wilms' tumor where it has been reported that its transactivating function is 1.5-fold higher than the 52-54 kDa WT1 isoform KTS (-)." (PMID 34845427, 2021).
Wilms tumor (continued). "This protein results from a chromosomal translocation involving breakage of chromosomes 11 and 22 at sites of genes known to be involved in Wilms’ tumor (WT1) and Ewing’s sarcoma (EWSR1), respectively." (PMID 34869013, 2021). "In the present study, we investigated the most effective kaffir lime leaf fractionated extract and the elucidated active compounds on the human Wilms’ tumor (WT1) gene expression in leukemic cells." (PMID 32178481, 2020). "Wilms tumor gene 1 (WT1) encodes a zinc-finger transcription factor initially identified as a tumor suppressor gene in Wilms’ tumor, but its overexpression in leukemia has led to consider WT1 as a potential oncogene." (PMID 33255335, 2020). "We developed DCs pre-pulsed with Wilms’ tumor (WT1) peptides in low-adhesion culture maturation (WT1-DCs)." (PMID 32231023, 2020). "In summary, WT1 mutant Wilms tumor cell lines have a limited and variable mesenchymal differentiation capacity." (PMID 33379206, 2020). "A high level of Erk1/2 phosphorylation was also observed in the Wt1-Igf2 Wilms tumor mouse model and was postulated to be due to Igf2 signaling through IGF1R activation." (PMID 33379206, 2020). "We were interested to study urinary exosomal expression for nephrin, renal Wilm’s Tumor (WT-1) and podocalyxin like protein 1(PODXL) in urine samples from placebo and linagliptin group." (PMID 32493344, 2020). "Of note, nuclear WT1 positivity is also found in desmoplastic small round cell tumor and Wilms tumor, which should be considered in morphologic differential diagnosis." (PMID 32155762, 2020). "Here we describe in detail the genetics, biological properties and molecular features of 11 WT1 mutant Wilms tumor cell lines that we have established to date." (PMID 33379206, 2020). "This subtype of WT1 mutant Wilms tumor corresponds to cells from an early embryonal stage of kidney precursors that still have the property to migrate." (PMID 33379206, 2020). "Wilms tumor 1 (WT1) is a tumor suppressor gene responsible for the development of familiar Wilms’ tumor, from which it takes its name." (PMID 32188030, 2020). "The induction of mesenchymal differentiation of these cells in vitro, points to the possibility that new agents can be tested for less toxic treatments of patients WT1 mutant Wilms tumors." (PMID 33379206, 2020). "These cell lines are unique and will contribute to study WT1 genetics in the context of Wilms tumor." (PMID 33379206, 2020). "WT1 was originally identified as a tumor suppressor gene in nephroblastoma, and was inactivated in tumors." (PMID 32210734, 2020). "Although Wilms' tumor gene 1 (WT1) was first cloned and identified as a tumor suppressor gene in nephroblastoma, subsequent studies have demonstrated that it can also play an oncogenic role in leukemia and various solid tumors." (PMID 32210734, 2020). "Although WT1 is first identified as a tumor suppressor in Wilms’ tumor, emerging evidence indicates that WT1 acts as an oncogene in various solid tumors and hematological malignancies." (PMID 32580769, 2020). "Most obviously, individuals who have deletions encompassing both PAX6 and WT1 should be screened for Wilms tumour as earlier detection almost certainly improves outcome." (PMID 30242502, 2019). "WT1 (Wilms’ Tumor) and LTL (lotus tetragonolobus lectin) proteins are frequently associated to glomerular and tubule areas respectively." (PMID 30814510, 2019). "The array is important to detect deletions encompassing WT1, which determine the need for continuing Wilms tumour screening and monitoring of renal function." (PMID 30242502, 2019). "WT1, named after Wilms’ tumour (nephroblastoma), is a transcriptional and post-transcriptional regulator that is expressed early in the urogenital ridge and plays an essential role in the development of the kidneys and gonads." (PMID 31816857, 2019).
Wilms tumor (continued). "WAGR syndrome (Wilms tumour, aniridia, genitourinary anomalies and mental retardation/intellectual disability), is caused by contiguous deletion of PAX6 and WT1 on chromosome 11p." (PMID 30242502, 2019). "Wilms tumors arise from the uninduced metanephric mesenchyme, where the Wilms tumor 1 (WT1) gene is expressed." (PMID 30068702, 2018). "Studies using gene expression data can provide an unbiased view of how WT1‐mutant Wilms tumors respond to chemotherapy." (PMID 29542868, 2018). "Here, we show that a more mature skeletal muscle differentiation is induced by chemotherapy in all WT1‐mutant Wilms tumors." (PMID 29542868, 2018). "We have successfully established cell lines from 11 WT1‐mutant Wilms tumors from patients having received 4‐ to 8‐week preoperative chemotherapy or were untreated before surgery." (PMID 29542868, 2018). "We show in this report that a significant number of genes associated with terminal myogenic differentiation are induced by chemotherapy and concomitantly a large fraction of cell cycle genes are down‐regulated in WT1‐mutant Wilms tumors." (PMID 29542868, 2018). "A comprehensive approach was used to identify key mechanisms responsible for the chemotherapy response of WT1‐mutant Wilms tumors." (PMID 29542868, 2018). "WT1 is a zinc finger-containing tumor suppressor shown to be involved in the etiology of Wilm’s tumor or nephroblastoma, a pediatric kidney malignancy." (PMID 29455671, 2018). "Wilms’ tumor 1 (WT1) gene was originally discovered as a tumor suppressor gene inactivated in a subset (∼15%) of pediatric renal cancers unrelated to RCC known as Wilms’ tumors." (PMID 29482572, 2018). "Chemotherapy‐treated WT1‐mutant Wilms tumors show a strong down‐regulation of many cell cycle genes." (PMID 29542868, 2018). "We conducted gene expression profiling of 11 chemotherapy and seven untreated WT1‐mutant Wilms tumors and analyzed up‐ and down‐regulated genes with bioinformatic methods." (PMID 29542868, 2018). "Cell culture experiments were performed from primary Wilms tumors and genetic alterations in WT1 and CTNNB1 analyzed." (PMID 29542868, 2018). "We established tumor‐derived cell cultures, analyzed evolution of genetic alterations, and compared gene expression profiles of untreated and treated WT1‐mutant Wilms tumors." (PMID 29542868, 2018). "Importantly, mutations in WT1 lead to Wilms' tumor disease, the most common pediatric kidney cancer, which is characterized by diffuse Wilms' tumor precursor lesions exhibiting large active chromatin domains resembling those found in human ESCs (hESCs), together with a disturbed MET process." (PMID 30459215, 2018). "The Wilms tumor 1 (WT1) gene encodes a zinc finger transcription factor and its inactivation is linked to Wilms tumors and some other cancers." (PMID 28257090, 2017). "Although WT1 was initially identified as a suppressor gene in Wilms’ tumor, it acts as an oncogene in malignancies such as leukemia, glioblastoma, and lung cancer." (PMID 29016617, 2017). "Wilms tumor, aniridia, genitourinary anomalies and mental retardation (WAGR) syndrome is a rare genetic disorder caused by heterozygous deletions of WT1 and PAX6 at chromosome 11p13." (PMID 29061165, 2017). "The WT1 gene, a TSG often mutated in pediatric Wilms’ tumor, was also down-regulated in TSC1/2-one-hit cells." (PMID 27682873, 2017). "Although initially described as a suppressor gene in Wilms’ tumors, the transcription factor WT1 acts as an oncoprotein in hematopoietic malignancies." (PMID 29152069, 2017). "Basp1 (brain abundant, membrane attached signal protein 1), encoding a membrane attached signaling protein, within module IV was originally identified as a transcriptional corepressor of Wt1 (Wilms’ tumor) that promoted apoptosis in diabetic nephropathy." (PMID 28931758, 2017).
Wilms tumor (continued). "The Wilms’ tumour gene 1 transcription factor (WT1) was first identified as a tumour suppressor gene in Wilms' tumour." (PMID 29152069, 2017). "We describe here a Wilms tumor (Wilms10) with an unusual tumor specific homozygous deletion of WT1 nested within a heterozygous 11p13 deletion." (PMID 27213811, 2016). "All our previously established WT1 mutant Wilms tumor cell lines have a limited life span, similar to normal human mesenchymal stem cells (hMSC)." (PMID 27213811, 2016). "Wilms Tumor 1 (WT1) is a zinc-finger transcription factor, initially reported in the literature as a mutated tumor suppressor in the setting of Wilms’ Tumor." (PMID 26907357, 2016). "Here we describe a stromal type Wilms tumor with a homozygous deletion of WT1 nested within a heterozygous 11p13 deletion and a CTNNB1 mutation." (PMID 27213811, 2016). "The Wilms tumor gene WT1 is a useful marker of clonal hematopoiesis and it has been shown to be a good marker of residual disease and it reflects the response to therapy." (PMID 27167495, 2016). "Wilms tumor 1 gene (WT1) has been firstly identified as a tumor suppressor gene in renal nephroblastoma, also known as Wilms tumor." (PMID 27014421, 2016). "It is highly desirable to establish tumor derived cell lines to develop cell culture model systems for Wilms tumors with deleted WT1 genes." (PMID 27213811, 2016). "A similarity of Wilms tumor derived cell lines with mutant WT1 to hMSCs was previously reported by our group." (PMID 27213811, 2016). "For the increased genes, the highest overlap was found between the Nes-Cre Wt1 conditional increased genes and the WT1-mutant Wilms' tumour increased genes (13 genes)." (PMID 26035382, 2015). "Wilms’ tumor gene 1 (WT1) was first identified as a tumor suppressor gene in Wilms’ tumor, a childhood kidney neoplasm; later findings demonstrated oncogenic properties in other malignancies including breast, lung, ovarian and brain tissue." (PMID 25929687, 2015). "In accordance with the comparison at the gene level, muscle-related terms (red nodes) strongly cluster with the Nes-Cre Wt1 conditional and/or WT1-mutant Wilms' tumours samples." (PMID 26035382, 2015). "At later stages the cells become committed to a renal fate, and subsequently Wilms' tumours arising after this step (the WT1-wild-type tumours) cannot form the ectopic tissues found in the WT1-mutant cases." (PMID 26035382, 2015). "For the decreased genes the biggest overlap was found in the intersection between the Nes-Cre Wt1 conditional and both sets of Wilms' tumour datasets (9 genes) or the Pax8+/CreWt1 conditional and both tumour sets (18 genes)." (PMID 26035382, 2015). "The Wilms’ tumor gene WT1 was originally isolated as a tumor suppressor gene in Wilms’ tumor, a childhood kidney cancer." (PMID 26090994, 2015). "Given the different development stages where nephron development in our mutant models is blocked, we decided to compare the genome-wide expression patterns of the mice to the two main groups of human Wilms' tumour (WT1-mutant and WT1-wild-type)." (PMID 26035382, 2015). "Comparison of the mutant mouse kidney expression data to Wilms' tumour data is consistent with a block in MET as the origin of WT1-mutant Wilms' tumours and highlights clear biological differences between these tumour types." (PMID 26035382, 2015). "The IGF-IR gene promoter also includes cis-elements for members of the early growth response family of zinc-finger proteins including the WT1 Wilms’ tumor suppressor, which, in contrast with Sp1, downregulates the expression of IGF-IR." (PMID 25884514, 2015).
Wilms tumor (continued). "To start elucidating the events that lead to Wilms' tumour formation, we analyzed the role of Wt1 before and after the MET, one of the candidate stages of origin of the tumours." (PMID 26035382, 2015). "Comparison of genome-wide expression data of these mutants to Wilms' tumour microarray data suggests the stages of origin of the WT1-mutant and WT1-wild-type tumour subsets, and further highlights their different developmental characteristics." (PMID 26035382, 2015). "For example, a deletion in case 16 encompassing WT1 and PAX6 caused 46,XY DSD, Wilms tumor, aniridia, and mental retardation, which is collectively referred to as WAGR syndrome." (PMID 26542297, 2015). "Although originally identified as a tumor suppressor gene in children with Wilms’ tumor, subsequent work has demonstrated that WT1 is overexpressed in a wide variety of tumor types, including acute myeloid leukemia (AML)." (PMID 25794157, 2015). "In the context of a single gene giving rise to alternatively spliced transcripts that produce proteins regulating transcription or splicing, CDX2 shares considerable similarity with the Wilms’ tumor gene, WT1." (PMID 25101906, 2014). "It is noteworthy that the locations of STAT3 and WT1 protein in primary Wilms’ tumor cells were found mostly located in the nucleus compared to prevalent cytoplasm expression in control normal cells near the tumor." (PMID 25474318, 2014). "Previous studies demonstrated that Wt1-Igf2 tumors recapitulate the histology and signature of gene expression of human Wilms tumors." (PMID 22875335, 2013). "Previously, both retroviral and lentiviral modification of T cells expressing recombinant T cell receptors against the Wilm’s tumour (WT1) antigen has been described and Phase 1 testing of an enhanced HLA-A2/WT1 peptide specific TCR has been initiated." (PMID 23840834, 2013). "We performed morphoproteomic profiling of DSRCT (EWS-WT1), Ewing’s sarcoma (EWS-FLI1) and Wilms’ tumor (WT1) to better understand the signaling pathways for selecting future targeted therapies." (PMID 23922674, 2013). "WT1 was originally identified as a tumor suppressor gene in Wilm’s tumor, and was subsequently found to be overexpressed in a variety of solid tumors." (PMID 23936312, 2013). "Wilms Tumor gene (WT-1) which is a tumor suppressor gene located on chromosome 11 at p13 found to be positive in 94.7% of patient with ovarian carcinoma was also positive in our patient." (PMID 23150837, 2012). "WT1 was initially discovered as a tumor suppressor in Wilms' tumor (WT), a pediatric kidney malignancy that affects approximately 1/10,000 children." (PMID 22244202, 2012). "The features favoring the diagnosis of blastemal Wilms tumor are young age and positivity of blastemal elements for vimentin, low molecular weight cytokeratin, epithelial membrane antigen, and WT1." (PMID 22312368, 2012). "More than 70% of DSRCT cases are positive for WT1, a finding which has also been shown with mesothelioma and Wilms' tumour." (PMID 21696639, 2011). "Although WT1 functions as a tumor suppressor in the formation of Wilms' tumors, recent findings have shown that wild-type WT1 is expressed in a variety of tumors from different origins that normally do not express WT1." (PMID 20122399, 2010). "The Wilms Tumor gene (WT1) product was initially defined as a tumor suppressor gene involved in the development of Wilm’s tumor, but today it is considered capable of performing oncogenic functions." (PMID 24281100, 2010).